RN7SL607P (RNA, 7SL, cytoplasmic 607, pseudogene)
Gene: Miscellaneous RNA gene on chromosome 20 (20,738,433 to 20,738,731, reverse strand). Ensembl gene ENSG00000278525.
Homologues: Orthologues: chimpanzee Metazoa_SRP (98% identical), macaque Metazoa_SRP (87% identical). Paralogues in human: RN7SL1 (84% identical), RN7SL3 (84% identical), RN7SL2 (83% identical), RN7SL464P (83% identical), RN7SL186P (80% identical), RN7SL386P (80% identical), RN7SL566P (80% identical), RN7SL220P (80% identical), RN7SL230P (80% identical), RN7SL45P (80% identical), RN7SL509P (80% identical), RN7SL543P (80% identical), and 702 more.